MIR548AJ2 (microRNA 548aj-2)
Synonyms: hsa-mir-548aj-2
Gene: MicroRNA gene on chromosome X (38,023,895 to 38,023,986, reverse strand). Ensembl gene ENSG00000221466.
Gene Ontology:
Biological process: miRNA-mediated post-transcriptional gene silencing
Cellular component: RISC complex
Diseases named in the same sentence as MIR548AJ2 in open-access papers:
MIR548AJ2 is named in the same sentence as 2 diseases in open-access papers, as found by Europe PMC text mining. Sharing a sentence is not in itself a finding about the gene and the disease. The quoted sentences say what the papers report.
Brugada syndrome (1 paper, 2023). A genetically heterogeneous condition characterized by complete or incomplete right bundle branch block accompanied by ST elevation in leads V1-V3. "At least seven genes putatively mapped by our significant non-reference TEs have been already associated with schizophrenia: LRRC4C, LRRC7, ST8SIA4, MGAM, ADAMTS1, MIR548AJ2 and SCN5A, which is also linked to the Brugada syndrome." (PMID 37244930, 2023).
MIR548AJ2 also shares sentences with these, for which no sentence is quoted: schizophrenia (1 paper).